CIITA (class II major histocompatibility complex transactivator)
Diseases named in the same sentence as CIITA in open-access papers (continued):
Sharing a sentence is not in itself a finding about the gene and the disease.
breast carcinoma (14 papers, 2012 to 2025). "Here, we comprehensively investigate the expression landscape of CIITA in breast cancer using publicly available multi-omics datasets, and examine its association with tumor-infiltrating immune cells, CIITA gene expression, and clinical prognosis." (PMID 40861816, 2025). "Through integrative bioinformatics analyses using The Cancer Genome Atlas (TCGA) and other datasets, we demonstrate that high CIITA expression is associated with favorable clinical outcomes and enhanced immune activation in breast cancer." (PMID 40861816, 2025). "We provide additional evidence for epigenetic regulation of CIITA linked to the decreased expression of cell surface MHC II in highly metastatic breast cancer cells." (PMID 22563434, 2012). "CIITA expression association with breast cancer clinicopathology was investigated." (PMID 40861816, 2025). "GSEA of TCGA cohorts revealed a significant high correlation between KAT2B and CIITA RNA expression levels in breast cancer." (PMID 40495188, 2025). "Future studies are warranted to explore the therapeutic utility of CIITA modulation in breast cancers and its potential synergy with immune checkpoint blockade or cancer vaccines." (PMID 40861816, 2025). "Collectively, the data reveal that CIITA modulates breast cancer metabolism by simultaneously suppressing oncogenic metabolic processes and activating pathways linked to anti-tumor immunity and cellular homeostasis." (PMID 40861816, 2025). "Immunohistochemical staining of breast cancer tissues further confirms CIITA protein expression patterns." (PMID 40861816, 2025). "In summary, our integrative analysis identifies CIITA as a pivotal immune regulator in breast cancer, linking its expression to improved clinical outcomes and robust antitumor immunity." (PMID 40861816, 2025). "Nevertheless, the specific role of CIITA in breast cancer remains largely unexplored." (PMID 40861816, 2025). "The development of CIITA-targeted therapies could revolutionize the treatment landscape for breast cancer, particularly in subtypes with poor immunogenicity and limited response to current immunotherapies." (PMID 40861816, 2025). "CIITA demonstrates prognostic biomarker potential in breast cancer." (PMID 40861816, 2025). "Multivariate Cox modeling established CIITA as an autonomous breast cancer prognostic determinant." (PMID 40861816, 2025). "Taken together, these data suggest that CIITA expression stratifies breast cancer patients into distinct therapeutic response groups and may inform personalized treatment strategies." (PMID 40861816, 2025). "Notably, in breast cancer constitutive CIITA expression was observed in poorly metastatic cases, indicating a correlation between gene expression and metastasis." (PMID 38893126, 2024). "Hypermethylation and recruitment of dysregulated methyltransferases were hypothesized as mechanisms for defective CIITA and HLA-II expression in metastatic breast cancer, but these studies were based on a presumed breast cancer cell line MDA-MB-435." (PMID 24475282, 2014). "However, the underlying mechanisms for E2-ERα inhibition of CIITA transactivation and STAT1 signaling in breast cancer are likely to be more diverse and complex." (PMID 24475282, 2014). "The ramifications of our study to tumors of the breast are clear and support previous findings regarding suppression of CIITA in breast cancer: breast tumors may increase metastatic properties by epigenetically targeting CIITApIV resulting in suppression of cell surface expression of MHC II." (PMID 22563434, 2012). "This study investigates the role of class II major histocompatibility complex transactivator (CIITA), a master regulator of major histocompatibility complex class II(MHC-II) gene expression, in breast cancer." (PMID 40861816, 2025). "Another study reports that downregulation of EZH2 results in significant increases in CIITA and HLA-DRA expression as well as increased cell surface expression of MHC II in breast cancer." (PMID 29132376, 2017).
breast carcinoma (continued). "Moreover, STAT1 signaling, necessary for CIITA pIV activation, and selected STAT1 regulated genes were variably downregulated by E2 in transfected and endogenous ERα positive breast cancer cells, whereas STAT1 signaling was noticeably augmented in ERα− breast cancer cells." (PMID 24475282, 2014). "In particular, how CIITA expression correlates with immune cell infiltration, MHC II expression levels, and patient outcomes across different breast cancer subtypes has not been systematically addressed." (PMID 40861816, 2025).
autoimmune disease (13 papers, 2012 to 2025). A disorder resulting from loss of function or tissue destruction of an organ or multiple organs, arising from humoral or cellular immune responses of the individual to their own tissue constituents. "CIITA has been implicated in immune function through association with autoimmune diseases or very recently with leprosy." (PMID 28100790, 2017). "However, other variants in the CIITA locus than rs3087456 have been reported in association with autoimmune disease warranting further exploration of this locus in the context of RA." (PMID 22461888, 2012). "DMF, an FDA‐approved drug for autoimmune diseases, was previously shown to block IFNγ‐induced CIITA expression." (PMID 41078003, 2025). "CIITA encodes the MHC class II transactivator, which is an important genetic factor that determines susceptibility to autoimmune diseases." (PMID 37346038, 2023). "In the gene-rich region of chromosome 16p13, several autoimmune disease-associated SNPs have also been identified in the neighboring SOCS1 and CIITA genes, as well as in intergenic regions." (PMID 23439554, 2013). "Also, it seems likely that CIITA is involved in other autoimmune disease, with multiple sclerosis being the most pronounced." (PMID 22461888, 2012). "The class II major histocompatibility complex transactivator (CIITA) acts as a transcriptional coactivator that regulates the MHC class II genes, IL-4, IL-10 and other immune-mediating genes, which has been implicated in various inflammatory and autoimmune diseases." (PMID 30069262, 2018). "This strategy was deployed in both the TyU19 and YTS109 products for autoimmune disease, in which healthy donor PBMC were edited to knock out HLA-A, HLA-B and CIITA, which are required for HLA-II expression." (PMID 41463563, 2025). "Additional immune-regulatory loci include MICA/MICB, CTLA4, PTPN22, CIITA, CLEC16A, CD274 (PD-L1), and NLRP1 (NALP1)—variants shared with other autoimmune diseases, underscoring common immune checkpoints rather than AAD-specific genes." (PMID 41465179, 2025). "Within this ~53 kB spanning intergenic region, which seems to play an important role in the pathogenesis of autoimmune diseases, the XL9 sequence is characterised by high acetylation levels—as confirmed by our results—and does not show an association with CIITA or the DNA-binding factor RFX." (PMID 30212590, 2018).
viral infection (12 papers, 2014 to 2025). "Optimal viral infection and appropriate CIITA and MHC‐II expression were determined in the mouse GB cell line GL261." (PMID 39535369, 2025). "While no apparent reduction of MHC-II expression in these cells was observed after infection, it is possible that CIITA transfection counteracts any effect of virus infection in our system as reported for SARS-CoV-2 and Ebola viruses." (PMID 37498934, 2023). "While no apparent effect was observed for MHC-II, it is possible that CIITA transfection counteracts any effect of virus infection in our system as reported for SARS-CoV-2 and Ebola viruses." (PMID 36482973, 2022). "Since CIITA has been implicated in resisting the endosomal entry of SARS-CoV-2, modulation of the FoxO3- CIITA signalling is likely to aid in managing the viral infection." (PMID 34102081, 2021). "The authors used a transposon-based screening approach to identify which activated or inactivated genes affect virus infection and then established that the CIITA transcription factor inhibited virus processing." (PMID 33235189, 2020). "For example, NLRC5 and CIITA/NLRA can translocate from the cytosol to the nucleus to regulate inflammation signaling during virus infection." (PMID 31681307, 2019). "CIITA (MHC class II transactivator) regulates major histocompatibility complex (MHC) class II expression in antigen presenting cells (APCs) It was reported that CIITA could play preventive or supportive roles in virus infections." (PMID 38826374, 2024). "MHC Class II Transactivator CIITA presents a particular interest in the field of anti-viral immunity as it may affect viral infection through two main activities." (PMID 35893677, 2022). "The MHC CIITA, which regulates MHC class II expression in antigen-presenting cells, has been reported to have either protective or supportive roles in viral infections." (PMID 40579376, 2025).
glioblastoma (11 papers, 2015 to 2025). The most malignant astrocytic tumor (WHO grade IV). "Using a CIITA-encoding plasmid, the human malignant glioma U87 cell lines and our proprietary human glioblastoma cell line GM2 were transfected, resulting in HLA-DR overexpression in both cell types." (PMID 38201622, 2023). "CIITA induces MHC class II expression in glioblastoma cells, endowing them with surrogate antigen-presenting capability that elicits robust CD4+ T cell-mediated adaptive anti-tumor immunity." (PMID 40861816, 2025). "Selective antigenic silencing is most evident in glioblastoma (GBM) hypermethylation or Polycomb occupancy at CIITA, NLRC5, TAP1/2, and HLA-A/B loci downregulates MHC-I/II expression without altering other immune programs." (PMID 41341594, 2025). "We developed a CIITA‐expressing adenovirus (Ad‐CIITA) that effectively transduces glioblastoma (GB) organoids, successfully inducing both CIITA and surface MHC‐II expression." (PMID 39535369, 2025). "Within this frame, it is important to outline that a similar modification of tumor microenviroment was obtained by using GL261 glioblastoma cells modified to express MHC class II molecules after stable transfection of CIITA." (PMID 39334370, 2024). "The visibility of tumor antigens can also be rescued by inducing the expression on tumor cells of MHC class II molecules after genetic modification with CIITA, as we have demonstrated in varius experimental tumor models including glioblastoma." (PMID 39334370, 2024). "Conclusion: these results question the therapeutic potential of CIITA-mediated immunotherapy in glioblastoma." (PMID 38201622, 2023). "Altogether, these results question the therapeutic potential of CIITA-mediated immunotherapy in glioblastoma." (PMID 38201622, 2023). "The major histocompatibility complex type II is downregulated in glioblastoma (GB) due to the silencing of the major transcriptional regulator class II transactivator (CIITA)." (PMID 38201622, 2023). "We show that genetic transfer of CIITA into the murine glioblastoma model cell line GL261 renders these cells MHC class II-positive and potent stimulators of an adaptive immune response in vivo when injected intracranially." (PMID 36993983, 2023). "Here, we report unprecedented positive results in terms of protection from glioblastoma growth in an animal experimental system after vaccination with glioblastoma GL261 cells stably expressing the MHC class II transactivator CIITA." (PMID 36993983, 2023). "It is therefore tempting to speculate that an oHSV-1 virus containing CIITA may synergically increase the stimulation of the tumor specific CD4 + T cells to reach complete rejection of in vivo established glioblastoma tumors." (PMID 39334370, 2024). "CIITA expression was assessed in 76 glioblastoma samples using immunohistochemistry." (PMID 38201622, 2023). "GL261-CIITA cells are a potent anti-glioblastoma vaccine, stimulating a protective adaptive anti-tumor immune response in vivo as a consequence of CIITA-driven MHC class II expression and consequent acquisition of surrogate antigen-presenting function toward tumor-specific CD4+ Th cells." (PMID 36993983, 2023). "This suggested that forced expression of CIITA in tumor cells could induce a potent antitumor response against glioblastoma." (PMID 38201622, 2023). "Here we explored the expression of key proteins involved in the HLA-I and HLA-II presentation machineries through proteomics and immunopeptidomics approaches, thereby revealing the antigenic landscape of three glioblastoma cell lines upon stable expression of CIITA." (PMID 33592498, 2021). "•CIITA-expressing glioblastoma cells express high levels of HLA-II complexes." (PMID 33592498, 2021). "Similarly to the results obtained with M14, we demonstrated that in glioblastoma cell line p48 protein increases the transcription of MHC II genes through CIITA activation." (PMID 26081906, 2015).
glioblastoma (continued). "We provide important details to indicate that glioblastoma cell-secreted CCL21 plays a dual role both in recruiting plasmacytoid dendritic cells via binding to CCR7 and activating plasmacytoid dendritic cells through the CCR7/ACKR4—β-arrestin/CIITA pathway." (PMID 39456552, 2024). "Here, we describe for the first time the application of our tumor vaccination strategy to glioblastoma, a tumor that does not express CIITA in a constitutive fashion but can be induced to do so after stimulation with IFN-γ, at least in vitro." (PMID 36993983, 2023).
Immunodeficiency (11 papers, 2008 to 2025). Failure of the immune system to protect the body adequately from infection, due to the absence or insufficiency of some component process or substance. "For example, CIITA is the class II major histocompatibility complex transactivator, which causes severe immunodeficiency if dysfunctional." (PMID 41396161, 2025). "Defects in human CIITA gene expression have been linked to several immune disorders." (PMID 18254971, 2008). "One key molecule involved in the regulation of basal HLA class II expression is CIITA, which is of pathologic relevance in rare, but severe immune disorders." (PMID 34359808, 2021). "The significance of the master regulator for MHC expression has been accentuated by previous studies linking changes in CIITA expression to the pathogenesis of immune disorders or cancer." (PMID 33939725, 2021). "The essential role of the master regulator of MHC-II gene expression has been emphasised by studies showing that altered CIITA expression contributes to neoplastic diseases and immune disorders." (PMID 30212590, 2018). "Whereas CIITA loss-of-function mutations leads to ineffectual MHC II transactivation and immunodeficiency, CIITA hyperactivation is associated with aberrant MHC II transactivation and chronic inflammation." (PMID 28094290, 2017). "Nonetheless, even “leaky” CIITA defects ultimately result in significant immunodeficiency, and nearly all patients, whether harboring nonsense or missense variants, require aggressive supportive therapy and early consideration of curative hematopoietic stem-cell transplantation (HSCT)." (PMID 41376631, 2025). "We also confirmed that the immunodeficiency in this mouse strain was not related to the CIITA transcriptosome complex, but resulted from a spontaneous H2-Aa point mutation, which led to the errant splicing of pre-mRNA and frameshift of protein." (PMID 35309308, 2022).
B-cell lymphoma (9 papers, 2012 to 2025). "Decrease or loss of MHC-II expression in B cell lymphoma has been associated with genetic alterations, such as CIITA deficiency, and is associated with poor survival in human B cell lymphoma." (PMID 39817454, 2025). "Genomic CIITA breaks were found to occur frequently in B-cell lymphoma patients; 38% of primary mediastinal B-cell lymphoma patients and 15% of classical Hodgkin’s lymphoma patients displayed them." (PMID 24137163, 2013). "The role of CIITA gene fusion products in B-cell lymphomas remains a field of considerable interest." (PMID 24137163, 2013). "Genomic breaks in the MHC CIITA gene are found in 38% of primary mediastinal B-cell lymphomas and result in downregulation of cell-surface MHC class II expression." (PMID 24409177, 2013). "We concluded that similarly to CIITA, EZH2, and CREBBP mutations, IRF8 variants may add to the pathogenesis of B cell lymphomas by impairing antigen presentation in the context of MHCII." (PMID 38996030, 2024). "Moreover, to validate whether the BAP1/IRF1/CIITA axis is a major regulator of MHC-II genes’ expression in B cell lymphoma, we restored IRF1 in BAP1-KO A20 cell followed by RNA-Seq analysis and FACS analysis." (PMID 39817454, 2025). "Promoter swap, involving the MHC class II transactivator (CIITA) and PD‐L1, was reported in primary mediastinal B‐cell lymphoma and Hodgkin lymphoma, leading to increased PD‐L1 expression." (PMID 37206267, 2023). "CIITA, a master regulator of MHC class II gene expression and truncated in B-cell lymphoma and Hodgkin disease, is found to fuse with DEXI in 48% of normal karyotype AML cases." (PMID 23251452, 2012). "In cHL and primary mediastinal B-cell lymphoma, genomic breaks of the major histocompatibility complex (MHC) class II transactivator CIITA have been demonstrated to be highly recurrent (15% and 38%, resp)." (PMID 22927872, 2012).